PUM2 (pumilio RNA binding family member 2)
Diseases named in the same sentence as PUM2 in open-access papers (continued):
Sharing a sentence is not in itself a finding about the gene and the disease.
colitis (2 papers, 2022 to 2026). Inflammation of the colon. "Pum2 deficiency aggravates colitis via macrophage-epithelial crosstalk driving inflammation and necroptosis." (PMID 41856997, 2026). "In dextran sulfate sodium (DSS)-induced colitis models, Pum2 deficiency exacerbated mucosal injury, accompanied by heightened macrophage inflammation." (PMID 41856997, 2026). "Mechanistically, Pum2 loss during colitis drives macrophage hyperactivation and TNFα-dependent epithelial necroptosis, which together intensify pathogenic macrophage-epithelial interactions and barrier breakdown." (PMID 41856997, 2026). "Intestine-specific knockout of Pum1 and Pum2 in mice significantly inhibits the progression of colitis-associated cancer in the AOM/DSS model." (PMID 35338151, 2022). "The dynamic downregulation of Pum2 in active inflammation underscores its potential as a therapeutic target for modulating macrophage-epithelial interactions and restoring intestinal barrier integrity in the context of colitis." (PMID 41856997, 2026).
colon cancer (2 papers, 2022 to 2025). "Furthermore, intravenous injection of nanoparticle-encapsulated anti-Pum1 and Pum2 siRNAs reduces colorectal tumor growth in murine orthotopic colon cancer models." (PMID 35338151, 2022).
colorectal cancer (2 papers, 2022 to 2023). A primary or metastatic malignant neoplasm that affects the colon or rectum. "Here, we report that Pum1 and Pum2 display increased expression in human colorectal cancer (CRC)." (PMID 35338151, 2022). "For example, it has recently been demonstrated that in human colorectal cancer (CRC), Pum1 and Pum2 are expressed at elevated levels and that the knockdown by siRNA of Pum1 and Pum2 in a mouse model of CRC inhibits tumour progression." (PMID 37747106, 2023).
gastric cancer (2 papers, 2022 to 2025). A primary or metastatic malignant neoplasm involving the stomach. "Studies on breast and gastric cancer have shown that RNA binding proteins such as PUM2 and Lin28B can bind to NRP1 mRNA, increasing its stability and expression, thereby affecting protein levels." (PMID 40806445, 2025).
glioma (2 papers, 2020 to 2021). A benign or malignant brain and spinal cord tumor that arises from glial cells (astrocytes, oligodendrocytes, ependymal cells). "This study found that the expression of UBE2I was significantly increased in glioma cells, which promoted PUM2 SUMOylation, led to the degradation of PUM2 protein, and inhibited the role of PUM2 protein in the degradation of CEBPD mRNA." (PMID 32997416, 2020). "This study found that the knockdown of UBE2I, CEBPD, and DSG2, and the overexpression of PUM2 in vitro all inhibited the capacities for migration, invasion, and VM in glioma cells." (PMID 32997416, 2020). "In this study, the expression of PUM2 in the tumor tissue of glioma patients was detected by qRT‐PCR, immunofluorescence, and western blot." (PMID 32997416, 2020). "UBE2I knockdown significantly promoted the expression of PUM2 protein in the cytoplasm, but did not significantly affect the nuclear and cytoplasmic distribution of PUM2 protein, while inhibiting the capacities for migration, invasion, and VM in glioma cells." (PMID 32997416, 2020). "In this study, by analyzing the database and experimental results, it was found that PUM2 can regulate the VM of glioma cells by binding CEBPD mRNA." (PMID 32997416, 2020). "Further, it was found that the expression of PUM2 was significantly decreased in the cytoplasm of glioma." (PMID 32997416, 2020). "In conclusion, this study found that the UBE2I/PUM2/CEBPD/DSG2 played crucial roles in regulating glioma VM." (PMID 32997416, 2020). "The experimental results found that the upregulation of UBE2I in glioma tissues and cells promotes the SUMOylation of PUM2, which decreases not only the stability of PUM2 protein but also decreases the inhibitory effect of PUM2 on CEBPD mRNA." (PMID 32997416, 2020). "Using the Hstudio M4 system, Transwell method, and three‐dimensional cell culture method, it was found that PUM2 overexpression significantly inhibited the capacities for migration, invasion, and VM in glioma cells compared with the NC group." (PMID 32997416, 2020). "In this study, by scanning TCGA database, it was found that the expression of PUM2 was positively correlated with the survival time of the patient, and found that PUM2 expression was decreased in glioma tissues." (PMID 32997416, 2020). "UBE2I knockdown, CEBPD knockdown, and PUM2 overexpression significantly inhibited the capacities for migration, invasion, and VM in glioma cells." (PMID 32997416, 2020). "The results of this study confirmed that UBE2I, CEBPD, and PUM2 have the potential to be new molecular targets, and the research on the treatment of gliomas needs to be further explored." (PMID 32997416, 2020). "Moreover, the upregulated UBE2I can promote the SUMOylation of PUM2 and ultimately promote glioma vasculogenic mimicry." (PMID 33898460, 2021). "Therefore, it was confirmed that UBE2I decreased the expression of PUM2 protein by SUMOylation in glioma cells, which further inhibited the capacities for migration, invasion, and VM in glioma cells." (PMID 32997416, 2020). "In summary, this study first discovered the abnormal expression of UBE2I, CEBPD, PUM2, and DSG2 in glioma tissues and cells." (PMID 32997416, 2020). "In this study, we found that PUM2 protein and SUMO2/3 protein were colocalized in glioma cells by laser scanning confocal microscopy." (PMID 32997416, 2020). "Our experimental results showed abnormal expression of UBE2I, PUM2, CEBPD, and DSG2 in glioma cells." (PMID 32997416, 2020). "Compared with the NC group, UBE2I knockdown, PUM2 overexpression, and CEBPD knockdown significantly inhibited the capacities for migration, invasion, and VM in glioma cells." (PMID 32997416, 2020). "The purpose of this study is to clarify the SUMO2/3‐induced SUMOylation in glioma, as well as the expression and interaction of PUM2, CEBPD, and DSG2, and the role of these molecules in regulating VM of glioma." (PMID 32997416, 2020).
glioma (continued). "Overexpression of PUM2 inhibited the capacities for migration, invasion, and VM in glioma cells, and our experimental results found that UBE2I inhibited the expression of PUM2 protein through SUMOylation, further promoting the capacities for migration, invasion, and VM in glioma cells." (PMID 32997416, 2020). "However, the role of SUMO2/3, PUM2, CEBPD, and DSG2 in glioma VM has not been reported." (PMID 32997416, 2020).
leukemia (2 papers, 2019 to 2020). A malignant (clonal) hematologic disorder, involving hematopoietic stem cells and characterized by the presence of primitive or atypical myeloid or lymphoid cells in the bone marrow and the blood. "PUM2 is highly expressed in myeloid leukemia cells and associated with regulating the growth of hematopoietic stem cells and leukemia cells." (PMID 32670859, 2020). "In addition to positively regulate stem cell proliferation, emerging evidences suggest that PUM2 is implicated in the pathogenesis of some cancers including leukemia." (PMID 30787206, 2019). "Studies on bladder cancer development showed that up regulation of PUM2 is associated with inhibited cancer growth, while one recent study on leukemia showed that PUM2 sustains myeloid leukemia cell growth." (PMID 30787206, 2019).
major depressive disorder (2 papers, 2018 to 2024). An episode of depression lasting two or more weeks without an intervening episode of mania. "CLDN-5, PUM1 and PUM2 mRNA levels in the post-mortem hippocampal sections of patients with bipolar (BP), schizophrenia (SCZ) and major depressive disorders (MDD) were measured as BBB integrity in the hippocampus is especially vulnerable to oxidative damage and other stress related stimuli." (PMID 38898501, 2024).
osteoporosis (2 papers, 2020 to 2023). A condition of reduced bone mass, with decreased cortical thickness and a decrease in the number and size of the trabeculae of cancellous bone (but normal chemical composition), resulting in increased fracture incidence. "The current study could not provide precise guidelines and protocols for the regeneration of damaged bone tissue and the treatment of osteoporosis using PUM2-KD MSCs or AAV9-siPum2." (PMID 37088847, 2023). "However, at this point, the focus of current study was to evaluate whether regulation of PUM2 expression would be of value as a candidate gene for bone tissue regeneration using stem cells or for osteoporosis gene therapy." (PMID 37088847, 2023). "Additionally, we confirmed that osteoporosis progression could be partly controlled by injecting AAV9-siPum2, indicating a potential gene therapy agent to control PUM2 expression in vivo." (PMID 37088847, 2023). "Therefore, we suggest that PUM2-mediated DLX5 regulation may be an important regulatory axis for osteogenic differentiation of human MSCs, and PUM2 could be a target for gene therapy to slow or prevent osteoporosis progression by modulating DLX5-mediated osteogenesis of MSCs." (PMID 37088847, 2023).
osteosarcoma (2 papers, 2020 to 2022). A usually aggressive malignant bone-forming mesenchymal neoplasm, predominantly affecting adolescents and young adults. "PUM2 represses osteosarcoma by competitively binding to the STARD13 3'UTR against miR-590-3p and miR-9." (PMID 34998399, 2022). "In osteosarcoma, the expression of PUM2 is low, and the overexpression of PUM2 inhibits the dryness of osteosarcoma." (PMID 32997416, 2020). "In osteosarcoma, the expression of PUM2 is significantly decreased." (PMID 32997416, 2020).
Parkinson's (2 papers, 2008 to 2011). "For instance, angiogenesis-related proteins were mainly enriched among PUM1 targets whereas the transcripts coding for proteins linked to Parkinson's disease were solely enriched among PUM2 targets." (PMID 18776931, 2008). "Notably, the mRNAs that were enriched in the Pum2-associated set included a group of genes linked to Parkinson's disease." (PMID 22016787, 2011).
adenoma (1 paper, 2022). A neoplasm arising from the epithelium. "H&E staining further revealed a significant decrease of adenomas when Pum1 and Pum2 were knocked down." (PMID 35338151, 2022).
Alzheimer disease (1 paper, 2018). A progressive, neurodegenerative disease characterized by loss of function and death of nerve cells in several areas of the brain leading to loss of cognitive function such as memory and language. "In support of this, PUM2 has been found to interact with multiple genes encoding functional proteins that are highly implicated in Alzheimer’s Disease, including amyloid precursor protein (APP), tau protein, and elF-4E." (PMID 30181804, 2018).
Ataxia (1 paper, 2023). Ataxia refers to impaired coordination of voluntary muscle movement. "Although there is no obvious ortholog of Puf3 in mammalian organisms, PUM1 and PUM2 are mammalian Pumilio proteins whose disruption have been associated with ataxia or mitochondrial phenotypes." (PMID 37216416, 2023).
cerebral malaria (1 paper, 2021). A sequestration of Plasmodium falciparum in the brain, which can cause coma and/or seizures. "The Pumilio protein PUM2, which is up-regulated in cerebral malaria patients, plays a role in the regulation of RIG-I signaling, which is essential for pathogen detection." (PMID 34746025, 2021).
colorectal tumors (1 paper, 2022). "Instead, we found that conditional knockout of Pum1 and Pum2 effectively blocked the occurrence and development of colorectal tumors." (PMID 35338151, 2022). "Furthermore, we show that intravenous injection of nanoparticles encapsulated with anti-Pum1 and Pum2 siRNAs significantly inhibits the growth of human colorectal tumors in mice." (PMID 35338151, 2022).
COVID-19 (1 paper, 2021). A disease caused by infection with severe acute respiratory syndrome coronavirus 2. "Expression of EPB41L4A-AS1 was increased in human induced pluripotent stem cell-derived cardiomyocytes (hiPSC-CMs), cultured cells infected with SARS-CoV-2 and PBMC of COVID-19 patients, and expression of PUM2 was also increased,)." (PMID 34940755, 2021).
epileptic seizures (1 paper, 2017). "Together with the fact that Pum2 is downregulated in postmortem brains of patients who suffered from epileptic seizures, we conclude that Pum2 is a key regulator of epileptogenic risk factors." (PMID 29046322, 2017). "Based on our results, we conclude that brain-wide knockdown of Pum2 causes a predisposition in developing animals to develop epileptic seizures that might be mediated by altered mRNA levels of known epileptogenic factors." (PMID 29046322, 2017).
Infertility (1 paper, 2020). "Notably, we found that a number of mRNAs that are enriched in TCam-2 cells compared to somatic gonadal tissue or cause infertility when mutated are under the control of PUM1 or PUM2 RNA regulons, which is in line with their divergent functions." (PMID 32316190, 2020). "Therefore, establishing the mechanisms underlying functional divergence of PUM1 and PUM2, including identification of their protein cofactors, may help in understanding their particular roles in human germ cells as well as human infertility, a problem affecting 15% of couples world-wide." (PMID 32316190, 2020).
leiomyoma (1 paper, 2022). A well-circumscribed benign smooth muscle neoplasm characterized by the presence of spindle cells with cigar-shaped nuclei, interlacing fascicles, and a whorled pattern. "In another study, an array CGH analysis was performed on 23 USMTs (14 STUMPs, 5 LMSs, 3 leiomyomas, and 1 undifferentiated sarcoma), suggesting that the PRKDC and PUM2 genes may have a prognostic role." (PMID 35976464, 2022).
lymphoma (1 paper, 2019). A malignant (clonal) proliferation of B- lymphocytes or T- lymphocytes which involves the lymph nodes, bone marrow and/or extranodal sites. "Here we validated PLAIDOH’s functional predictions for RP11-960 L18.1, confirming that it is not a cis-regulatory lncRNA for PLCG2, but rather likely acts in the cytoplasm by interacting with one or more RBPs (NF90, KHDRBS1, PUM2) to promote the growth of lymphoma cells." (PMID 30767760, 2019).
melanoma (1 paper, 2021). A malignant, usually aggressive tumor composed of atypical, neoplastic melanocytes. "However, in both melanomas secondary copy number alterations of the CYSLTR2 locus (chromosome 13q) were observed as well: PUM-1 showed loss of the wild-type allele, while in PUM-2 the mutant allele was gained." (PMID 33588787, 2021).
non-small cell lung carcinoma (1 paper, 2022). A group of at least three distinct histological types of lung cancer, including non-small cell squamous cell carcinoma, adenocarcinoma, and large cell carcinoma. "In non-small cell lung cancer, tumor suppressor miR-340 directly binds to the 3′UTR of Pum1 and Pum2 mRNA to inhibit their expression, thus reducing PUM1 and PUM2 that are required for the miR-221/222 interaction with the p27 3′UTR64." (PMID 35338151, 2022).
oesophageal cancer (1 paper, 2025). "In other studies The increased expression of UBE2D3 and PUM2 is associated with a better prognosis in patients with oesophageal cancer." (PMID 40524221, 2025).
sarcoma (1 paper, 2022). A usually aggressive malignant neoplasm of the soft tissue or bone. "We identified upregulation of Pum2, Puf60, and Fus (fused in sarcoma) known as translation repressors." (PMID 35754828, 2022).
status epilepticus (1 paper, 2018). Status epilepticus is defined as a continuous seizure lasting more than 30 min, or two or more seizures without full recovery of consciousness between any of them. "In line with this, patients with medically refractory TLE have reduced neocortical PUM2, and rats treated with pilocarpine leading to status epilepticus and subsequent spontaneous seizures days to weeks later also demonstrate a similar reduction in cortical and hippocampal PUM2." (PMID 30181804, 2018). "Additionally, pilocarpine-treated rats that developed status epilepticus still had reduced hippocampal and cortical PUM2 up to 60d later, a time point where spontaneous epileptiform activity develops and closely models TLE pathogenesis." (PMID 30181804, 2018).
triple-negative breast carcinoma (1 paper, 2020). An invasive breast carcinoma which is negative for expression of estrogen receptor (ER), progesterone receptor (PR), and human epidermal growth factor receptor 2 (HER2). "PUM2 was mainly distributed in the cytoplasm, and luminal A and triple negative breasts cancer tissues had decreased PUM2 expression compared to paracancerous tissues." (PMID 32670859, 2020).
uterus cancer (1 paper, 2021). "In the case of PUM2, it was overexpressed in almost all samples, except ovarian and uterus cancer tissues, where the RNA expression level was lower than in healthy tissues." (PMID 33401540, 2021).
ZIKV infection (1 paper, 2024). "To study the impact of ZIKV infection on IGF2BP2 association with endogenous RNAs, we decided to focus our analysis on three known IGF2BP2 mRNA ligands namely CIRBP, TNRC6A, and PUM2." (PMID 39565347, 2024). "More specifically, it has been shown that ZIKV infection decreases m6A content of CIRBP mRNA and increases the one of PUM2 and TNRC6A mRNAs." (PMID 39565347, 2024).